ZBTB44 (zinc finger and BTB domain containing 44)
Description:
May be involved in transcriptional regulation.
Synonyms: BTBD15; ZNF851; HSPC063
Tractability: PROTAC: UniProt records ubiquitination sites on it; its protein half-life has been measured.
Target class: Transcription factor
Gene: Protein-coding gene on chromosome 11 (130,226,677 to 130,314,917, reverse strand). Ensembl gene ENSG00000196323.
Subcellular location: Nucleus
Subcellular location (Human Protein Atlas): Nucleoplasm
Gene Ontology:
Molecular function: protein binding
Cellular component: nucleus
Genetic constraint (gnomAD): Loss-of-function variants: 14 observed, 48.76 expected, observed/expected ratio (o/e) 0.29, 90% interval 0.19 to 0.45. The upper end of that interval is the gene's LOEUF score, 0.45, which puts it in group 1 of 6, group 1 being the genes least tolerant of losing a copy. Missense variants: 472 observed, 700.96 expected, observed/expected ratio (o/e) 0.67, 90% interval 0.62 to 0.73. Synonymous variants: 227 observed, 247.34 expected, observed/expected ratio (o/e) 0.92, 90% interval 0.82 to 1.02.
Homologues: Orthologues: chimpanzee ZBTB44 (100% identical), macaque ZBTB44 (98% identical), dog ZBTB44 (98% identical), pig ZBTB44 (97% identical), rabbit ZBTB44 (97% identical), mouse Zbtb44 (96% identical), guinea pig ZBTB44 (95% identical), rat Zbtb44 (95% identical), tropical clawed frog zbtb44 (88% identical), zebrafish zbtb44 (53% identical), Drosophila melanogaster Opbp (7% identical). Paralogues in human: ZNF618 (15% identical), FIZ1 (11% identical).
Diseases named in the same sentence as ZBTB44 in open-access papers:
ZBTB44 is named in the same sentence as 6 diseases in open-access papers, as found by Europe PMC text mining. Sharing a sentence is not in itself a finding about the gene and the disease. The quoted sentences say what the papers report.
acute lymphoblastic leukemia (1 paper, 2021). Leukemia with an acute onset, characterized by the presence of lymphoblasts in the bone marrow and the peripheral blood. "Furthermore, circZBTB44 (Zinc Finger and BTB Domain Containing 44) and circZNF609 are both upregulated in acute lymphoblastic leukemia of which especially circZNF609 has a known oncogenic potential in multiple other cancers as well." (PMID 33920880, 2021).
lymphoma (1 paper, 2011). A malignant (clonal) proliferation of B- lymphocytes or T- lymphocytes which involves the lymph nodes, bone marrow and/or extranodal sites. "Four antigens, TCEB3, BECN1, c14orf93, and ZBTB44, showed more frequent recognition by lymphoma patients' sera." (PMID 21887344, 2011). "Of particular interest for future investigation are the two previously uncharacterised genes, c14orf93 and ZBTB44, both of which are differentially expressed in lymphoma-derived cell lines." (PMID 21887344, 2011). "However, this does not exclude the possibility that the five antigens preferentially recognised by sera from patients (TCEB3, BECN1, CEP250, c14orf93 and ZBTB44) may have a role in the pathobiology of lymphoma." (PMID 21887344, 2011).
myeloma (1 paper, 2011). "ZBTB44 and c14orf93 were differentially expressed, with ZBTB44 showing highest expression levels in one B-NHL and two myeloma cell lines and most frequent upregulation (5/9) in cell lines derived from T-cell malignancies." (PMID 21887344, 2011).
peripheral T-cell lymphoma (1 paper, 2014). "Among candidate molecules involved in these partially unknown events we identified by in silico analysis a transcription regulator, ZBTB44 which appears expressed in peripheral T-cell lymphoma and interacts with SMAD pathway protein like SMURF2 mediating resistance to MAPK pathway inhibitors." (PMID 25437182, 2014).
cancer (3 papers, 2011 to 2025). A tumor composed of atypical neoplastic, often pleomorphic cells that invade other tissues. "Yeast-two-hybrid studies have identified binding of ZBTB44 to components of the Smad signalling pathway, which is regulated by members of the TGFβ superfamily and can be disrupted in cancer." (PMID 21887344, 2011).
ZBTB44 also shares sentences with these, for which no sentence is quoted: tumour diseases (1 paper).